ETV3L (ETS variant transcription factor 3 like)
Description:
Transcriptional regulator.
Synonyms: FLJ16478
Tractability: PROTAC: ubiquitination databases record sites on it.
Gene: Protein-coding gene on chromosome 1 (157,092,043 to 157,117,877, reverse strand). Ensembl gene ENSG00000253831.
Subcellular location: Nucleus
Subcellular location (Human Protein Atlas): Nucleoli; Nucleoplasm; Cytosol
Gene Ontology:
Molecular function: protein binding; DNA-binding transcription factor activity, RNA polymerase II-specific; DNA-binding transcription factor activity; sequence-specific DNA binding
Biological process: cell differentiation; regulation of transcription by RNA polymerase II; regulation of DNA-templated transcription
Cellular component: nucleus
Genetic constraint (gnomAD): Loss-of-function variants: 30 observed, 28.02 expected, observed/expected ratio (o/e) 1.07, 90% interval 0.8 to 1.45. The upper end of that interval is the gene's LOEUF score, 1.45, which puts it in group 6 of 6, group 1 being the genes least tolerant of losing a copy. Missense variants: 443 observed, 464.42 expected, observed/expected ratio (o/e) 0.95, 90% interval 0.88 to 1.03. Synonymous variants: 186 observed, 190.14 expected, observed/expected ratio (o/e) 0.98, 90% interval 0.87 to 1.11.
Homologues: Orthologues: chimpanzee ETV3L (98% identical), macaque ETV3L (92% identical), dog ETV3L (75% identical), rabbit ETV3L (75% identical), mouse Etv3l (64% identical), rat Etv3l (60% identical), tropical clawed frog etv3l (49% identical). Paralogues in human: ETV3 (46% identical), ERF (40% identical), ERFL (35% identical), FLI1 (20% identical), ELF4 (19% identical), ERG (19% identical), ELK4 (19% identical), ETS1 (18% identical), ELK1 (18% identical), ETS2 (17% identical), FEV (17% identical), ETV4 (17% identical), and 16 more.
Diseases named in the same sentence as ETV3L in open-access papers:
ETV3L is named in the same sentence as 2 diseases in open-access papers, as found by Europe PMC text mining. Sharing a sentence is not in itself a finding about the gene and the disease. The quoted sentences say what the papers report.
tumor (2 papers, 2023 to 2024). "The genes expression levels in the model were detected by qRT-PCR, and the results showed that they were highly expressed in 20 pairs of tumor and normal tissues (UNCX, SLC6A3, AGAP2-AS1, LINC00968, PTX3 and SBSPON), while ITPRID1, DCST2, ETV3L, and ENSG00000261327 were down-regulated." (PMID 36647156, 2023).
ETV3L also shares sentences with these, for which no sentence is quoted: ovarian carcinoma (1 paper).